SHH (sonic hedgehog signaling molecule)
Diseases named in the same sentence as SHH in open-access papers (continued):
Sharing a sentence is not in itself a finding about the gene and the disease.
breast carcinoma (continued). "Moreover, the observed co-activation of JAK2-STAT3 and SHH signaling pathways suggests that combination of JAK2 and SMO inhibitors may synergize against TNBC and HER2-enriched breast cancers." (PMID 32957513, 2020). "SHH and GLI are both members of the Hh signalling cascade which was first described in the fruit fly Drosophila and it might be reasonable to assume that this signalling pathway is conserved and active in a proportion of human breast cancers." (PMID 19706168, 2009). "The database analysis of the Hedgehog pathway markers (SHH, PTCH1, SMO, GLI1, and GLI2) revealed that the Hedgehog pathway is activated in breast cancer tissues, and its high expression is not conducive to a patient’s survival." (PMID 36142286, 2022). "Other Hedgehog signaling factors like SHH, PTCH1, and GLI2 are overexpressed in breast cancer, but their connection to EMT is not well established in breast cancer." (PMID 31075939, 2019). "Since GLI1 is supposed to be a direct downstream target of Hh signalling in model organisms like Drosophila we wanted to decipher whether there is a correlation between the SHH and GLI1 expression patterns in human breast cancer and normal human breast tissues." (PMID 19706168, 2009).
glioma (58 papers, 2009 to 2025). A benign or malignant brain and spinal cord tumor that arises from glial cells (astrocytes, oligodendrocytes, ependymal cells). "Similar to gliomas, dysregulation of the SHH signalling pathway has been implicated in MB pathogenesis." (PMID 39568072, 2024). "GLI1 (glioma-associated transcription factor 1), a target of SHH signaling first identified in human glioma, is a modulator of the expression of stemness genes and self-renewal of CD133+ GSCs, and plays a key role in tumorigenesis." (PMID 32722427, 2020). "Activation of PI3K/AKT pathway and SHH/Gli1 pathway is associated with glioma progression." (PMID 36056982, 2022). "Furthermore in the context of gliomas, the SHH pathway is associated with specific tumour grades." (PMID 39568072, 2024). "In case of glioma, reactive astrocytes exhibit the localized expression of sonic hedge-hog (SHH) and Gli signaling within the perivascular niche, which correlates with the increasing grade of glioma." (PMID 41268299, 2025). "Mechanistically, NCOA4 overexpression inhibits the progression of glioma by suppressing the SHH pathway." (PMID 40794264, 2025). "In this study, NCOA4 was shown to repress glioma progression partially through inhibiting the SHH pathway." (PMID 40794264, 2025). "Further research has examined the expression of SHH pathway components in different glioma subtypes." (PMID 39568072, 2024). "Notch signalling synergizes with SHH signalling during nervous system development and plays a crucial role in oncogenesis, including CNS tumours such as gliomas, MBs, meningiomas, and choroid plexus papillomas." (PMID 39568072, 2024). "Gliomas pose significant challenges due to their aggressive nature; however, targeting the SHH pathway in GBM stem cells shows promise for therapeutic intervention." (PMID 39568072, 2024). "For example, histone deacetylase 6 (HDAC6) inhibition can trigger glioma stem cell differentiation by suppressing SHH signaling." (PMID 37830570, 2023). "SCUBE2 participates in SHH signaling and, when overexpressed, decreases glioma cell proliferation, migration, and invasion." (PMID 37628788, 2023). "We confirmed that SHH-stimulated ciliary SMO in S7 parental glioma cells was blocked by pretreatment with GDC-0449." (PMID 37830570, 2023). "The recent research shown that the combined with inhibitors of PI3K/Akt/mTOR and SHH is obviously better therapeutic effect than the single inhibitor for glioma." (PMID 35935338, 2022). "Here, through RNA-seq analysis and further validation, we found that part of the function of EN1 in glioma cells was achieved through regulating SHH pathway activity." (PMID 35163043, 2022). "Hedgehog/Gli1 pathways are often found overactivated in GBM, and Sonic Hedgehog (SHH) is the most researched hedgehog in EMT in gliomas." (PMID 36338770, 2022). "For instance, miR-326 can effectively suppress proliferation, and induce apoptosis in glioma cells via attenuating the activation of the SHH/GLI1 pathway." (PMID 36100906, 2022). "Recently, aspirin was reported to exert its antineoplastic property in glioma by abrogating the tumorigenic effect of the SHH/GLI1 signaling pathway, especially sensitizing the malignant glioma cells resistant to temozolomide (TMZ) therapy." (PMID 33494284, 2021). "Studies show that astrocytes with activated sonic hedgehog (SHH) signaling pathways are localized mainly in the glioma perivascular niche." (PMID 34084145, 2021). "Further characterization revealed that SHH-mediated GLI1 signaling regulated the self-renewal of CD133+ glioma CSCs." (PMID 32957513, 2020). "Given that the GLI1 amplification was discovered in gliomas, it is self-evident that aberrant SHH signaling plays a central role in glioma pathogenesis and tumor progression." (PMID 32957513, 2020).
glioma (continued). "Administration of cyclopamine, an inhibitor of SHH signaling, suppresses the proliferation of several glioma cell lines in vitro." (PMID 29867331, 2018). "Collectively, aspirin has a therapeutic potential for SHH/GLI1 targeted therapy against glioma cells." (PMID 28446712, 2017). "Here we confirm that aspirin exerts antineoplastic property in glioma by abrogating the tumorigenic effect of the SHH/GLI1 signaling pathway and acquire in-depth knowledge of sensitizing route of aspirin to TMZ therapy." (PMID 28446712, 2017). "Aspirin acted as the glioma growth-inhibitory and pro-apoptosis roles by inhibiting the SHH/GLI1 pathway and reprogramming the epithelial to mesenchymal transition (EMT)." (PMID 28446712, 2017). "Aspirin alone was used to treat glioma cell lines, and that concentrations of aspirin from 1 to 10 mM inhibited the SHH/GLI1 signaling pathway significantly." (PMID 28446712, 2017). "Tumor ECs expressed SHH in a PDGF-driven mouse glioma model, providing a potential mechanism for GLI1 activation in GSCs." (PMID 26977157, 2016). "Multiple studies have reported that the growth of some GBM tumors and glioma-derived stem cells is activated by the SHH signaling pathway." (PMID 26760767, 2016). "A third signaling pathway implicated as a central mediator in the pathogenesis of glioma and glioma stem cells (GSCs) is the Sonic Hedgehog (SHH)." (PMID 27043632, 2016). "Consistent with the RT-PCT and Western Blot analysis of HH signal cascade components, the stimulating effect of SHH was detectable solely in the CD133+ glioma population, the proliferation index in CD133− cells remained unaffected." (PMID 24978848, 2014). "Since the HH signaling acts as a mitogenic factor for glioma stem cells, we investigated the potential of SHH for sensitizing of highly therapy resistant GSC to an endogenous nucleoside analogue-based radiotherapy." (PMID 24978848, 2014). "In case of Glioma, we considered the over expression of hedgehog ligand SHH, i.e. the input value for SHH in our model was considered as “1” or “ON” throughout the simulation." (PMID 23935937, 2013). "As it is known that human gliomas and tumorigenic NSCs express SHH and comprise cells that simultaneously express neuronal and glial markers, this morphogene was associated with brain tumor formation and/or growth." (PMID 23162429, 2012). "To investigate whether NCOA4 exerts its inhibitory effect on glioma cell growth via the SHH pathway through the regulation of PTCH1, we knocked down PTCH1 in NCOA4-overexpressing GBM cells by transfecting them with siRNA-PTCH1." (PMID 40794264, 2025). "SHH signalling influences glioma growth and development through various mechanisms." (PMID 39568072, 2024). "This differential expression suggests that enhanced PTCH1 expression and SHH pathway activation are involved in brainstem gliomas, potentially explaining the differences in malignant behaviour between brainstem and hemispheric gliomas." (PMID 39568072, 2024). "Similarly, KLHDC8a stimulates glioma stem cell growth by promoting ciliogenesis and SHH pathway activation." (PMID 37830570, 2023). "While the SHH pathway appears overactive in a significant fraction of GBMs, little research has been done to understand the relationship of SHH and cilia in low- or high-grade glioma." (PMID 37830570, 2023). "In addition, aspirin sensitizes malignant glioma cells to temozolomide therapy by inhibiting the SHH/GLI1 signaling pathway, preventing most GLI1 translocation into the nucleus and resulting in higher expression levels in the cytoplasm." (PMID 35785194, 2022). "Suppression of SHH-Gli signaling markedly inhibits glioma cell migration and invasion, and SHH-Gli signaling may promote astrocyte activation in the perivascular niche surrounding the glioma, thus facilitating glioma invasion." (PMID 35448036, 2022).
glioma (continued). "Moreover, dysregulation of SHH signaling leads to enhanced proliferation of precursor cells likely to be involved in initiating the formation of gliomas." (PMID 34084145, 2021). "Similarly, morphogenic factors including WNT and SHH play important roles in microglia/astrocytes glioma crosstalk, recapitulating developmental programs of the tissues and organs during early embryogenesis." (PMID 34439999, 2021). "GLI1 activity in GBM is also regulated through crosstalk with other pathways including Ras, Myc, and Akt, which may contribute to resistance to SHH inhibitors in gliomas." (PMID 32957513, 2020). "Glioma-associated oncogene homolog 1 (Gli-1), originally identified in human glioma cells, is a zinc finger-containing transcription factor and the main nuclear mediator of the Sonic Hedgehog (SHH) signaling pathway that regulate cell proliferation and differentiation during CNS development." (PMID 29867331, 2018). "Dysregulated levels of Arl13b in glioma cells may have significant consequences on the SHH signaling pathway and tumor cell proliferation." (PMID 30410731, 2018). "In conclusion, our studies revealed that aspirin could inhibit glioma cells proliferation, induce apoptosis through SHH/GLI1 signaling pathway and aspirin potentially attenuate intrinsic and non-canonical TMZ resistance." (PMID 28446712, 2017). "Moreover, human gliomas display a stemness signature, and SHH-GLI signaling regulates the expression of stemness genes (e.g. Nanog, Oct4, Sox2, CD133) and the self-renewal of CD133(+) glioma cancer stem cells." (PMID 29079783, 2017). "The Gli1 transcription factor is one of the SONIC Hedgehog (SHH) pathway target genes, and it was found that HH-Gli signaling was essential for the maintenance of cancer stem-like cells in human gastric cancers and gliomas." (PMID 26769843, 2016). "Also our following observation concerning misregulation of miR-324-5p, engaged in the tumorigenesis of various cancers including glial tumors, suggests SHH contribution in PA biology as probably the consequence of changed progenitor differentiation." (PMID 26497896, 2015). "The inactivation of the SHH/GLI1 pathway mediated the anti-glioma effects of curcumin." (PMID 26563263, 2015). "Therefore to simulate the Glioma scenario in our study we considered the logical states of SHH, HFU, ULK3, ERK12, RAS, TWIST as “1” or “ON”." (PMID 23935937, 2013). "Our previous findings implicated a relationship between ARL13B and SMO in glioma cells that may, in part, be independent of SHH." (PMID 37830570, 2023). "The oncogenic role of MDK, promoting proliferation and pharmacological resistance in glioma, may involve the release of Sonic Hedgehog (SHH) from LRP2 sequestration in oligodendrocytes, thus functioning to activate one of the best-known activators of proliferation and stemness of brain tumors." (PMID 33155039, 2020). "Interestingly, a significant number of gliomas also respond to SHH." (PMID 30842728, 2019). "Additionally, it serves as a direct transcriptional regulator of SHH in glioma cells." (PMID 29914077, 2018). "Subsequently, to investigate the aspirin associated apoptotic route via SHH/GLI1 inhibition at protein level, Western blot showed that Caspase-3, Bax and cleaved PARP increased in a dosedependent manner and that Bcl-2, an anti-apoptosis protein, decreased in the glioma cells treated by aspirin." (PMID 28446712, 2017). "Experimental inhibition of the SHH pathway with the SHH antagonist LDE225 and the interfering RNA molecules applied with a lentivirus resulted in autophagic cell death of glioma stem cells expressing the stem cell marker CD133." (PMID 39062119, 2024). "We first examined the relationship of ARL13B expression and another key ciliogenesis gene, IFT88, with the expression of other SHH pathway genes (SMO, GLI2, and SHH) in low-grade glioma (LGG) and high-grade glioblastoma (GBM) using TCGA datasets." (PMID 37830570, 2023).
glioma (continued). "This miRNA targets GICs (glioma-initiating cells), which confer resistance to glioma cells against TMZ treatment, as well as inhibits the CXRC4 receptor, which, in turn, disrupts the SHH signaling pathway, thus resulting in preventing tumor progression." (PMID 37371047, 2023). "SHH/GLI1 signaling pathway was important to maintain the growth invasion and anti-apoptosis of glioma cell." (PMID 28446712, 2017). "The regulation of SOX2 by SHH occurs in neural and brain stem cells, and the pharmacological inhibition of these pathways silences SOX2 expression and impairs glioma cells’ tumorigenic activity." (PMID 27822457, 2016). "Apart from SHH, experimental evidence also showed that ERK12, TWIST and RAS proteins were up regulated during Glioma and these were known to have a direct effect on the abnormal activation of GLI1 and GLI2." (PMID 23935937, 2013). "On the other hand SHH, SMO, GLI1, GLI2, GLI3_A (core Hedgehog pathway molecules) were activating the other proteins in both normal as well as Glioma scenarios." (PMID 23935937, 2013). "We established 11 low passage glioma cell lines in N2 supported DMEM/F12 medium containing 2% FCS with a growth factor cocktail consisting of FGF2, PDGF-AA and SHH." (PMID 23630597, 2013). "A recent study demonstrates that SHH signaling regulates the expression of stemness genes and the self-renewal of CD133+ glioma CSCs." (PMID 23443123, 2012). "We discovered for the first time that NCOA4 can regulate glioma progression through the SHH pathway, not just by mediating ferroptosis." (PMID 40794264, 2025). "Moreover, glioma patients with higher NCOA4 expression exhibit longer OS, and NCOA4 suppresses glioma progression through the SHH pathway." (PMID 40794264, 2025). "TAAs promote glioma invasion through the activation of several signaling pathways, such as nuclear factor kappa-B (NF-κB), interleukin (IL)-6/JAK/STAT, and sonic hedgehog (SHH) signaling." (PMID 35448036, 2022). "Moreover, in gliomas, the inhibition of CXCR4 leads to the disruption of the sonic hedgehog (SHH)-GLI-NANOG network, and is crucial for maintaining the self-renewal, proliferation, therapeutic resistance, and angiogenesis of glioblastoma cells in rat." (PMID 34638956, 2021). "Consistent with our stimulation study, the capacity of SHH to modulate proliferation of GSC resulted in an approx. twofold increase of [I-125]ITdU uptake in CD133+ cells (4.9%±0.6% vs. 2.5%±0.6% in CD133+ and CD133− glioma cells, respectively)." (PMID 24978848, 2014). "Several types of tumors (basal cell carcinomas, gliomas, medullablastomas, and prostate cancer) express abnormally high levels of GLI proteins or increased SHH pathway activation, which may be targets for therapy." (PMID 22859956, 2012). "The differential response of glioma stem cells to SHH ligand, as compared to non-stem glioblastoma cells, highlights the potential of SHH pathway-targeted approaches as an effective single-cell killing strategy specifically against the stem-like tumor subpopulation." (PMID 40894044, 2025). "Thus, how these findings relate to glioma cells and whether the relationship between ARL13B and SMO is SHH-dependent remains unclear." (PMID 37830570, 2023). "The top pathways which were enriched in all adult glioma subtypes were pathways enriched for cell cycle, DNA repair, translation, splicing, oncogenic signaling pathways such as RAS pathway, Notch pathway, MHC pathway, PI3K/AKT Signaling, Wnt pathway, SHH pathway." (PMID 36918656, 2023). "The relationship between ARL13B, SMO, and GLI2 may be independent of SHH expression in glioma." (PMID 37830570, 2023). "Moreover, the SHH pathway is thought to be activated in primary GBM and glioma cell lines, leading to the overexpression of some drug efflux molecules (e.g., ABCB1, ABCG2 [BCRP], and ABCC1 [MRP1]), and MGMT and BMI1, which may explain its association with therapy-resistance." (PMID 32722427, 2020).
glioma (continued). "Studies demonstrate that the SHH pathway is active in grade II and III gliomas but not in grade IV de novo GBM’s." (PMID 39568072, 2024). "Collectively, these data suggest that increasing functional ARL13B inside the cilium leads to the lengthening of glioma cilia and a distal tip accumulation of SMO that is independent of exogenous SHH exposure." (PMID 37830570, 2023). "As a vital negative component of the Sonic Hedgehog (SHH) signaling pathway, PTCH1 participates in the suppression of glioma growth and its inhibition by miR-9 can induce tumor growth both in our study and in a previous report." (PMID 30795814, 2019). "Cyclopamine, an inhibitor of the SHH pathway, was also proved effective in reducing SOX2 expression and inducing cytotoxicity in in vitro studies, but unlike rapamycin, its combination with TMZ did not increase the sensitivity of glioma cells to chemotherapy." (PMID 27822457, 2016). "Similarly, we reported that Arl13b overexpression promotes SMO localization to GBM cilia in the absence of SHH, and that high levels of ARL13B and SMO expression in the tumors of glioma and gastric tumor patients was positively correlated with shortened post-diagnosis survival in these patients." (PMID 30842728, 2019).